NCOA2 (nuclear receptor coactivator 2)
Diseases named in the same sentence as NCOA2 in open-access papers (continued):
Sharing a sentence is not in itself a finding about the gene and the disease.
Obesity (8 papers, 2011 to 2024). Accumulation of substantial excess body fat. "Furthermore, knockout NCOA2-/- mice are protected against obesity, showing lean phenotype and decreased expression of genes involved in the uptake and storage of FA." (PMID 24666776, 2014). "As we illustrated in network pharmacologic analysis, these compounds might work in combination with other active compounds to attenuate obesity via modulating major targets including PTGS2, ADRB2, and NCOA2." (PMID 36928463, 2023).
spindle cell rhabdomyosarcoma (8 papers, 2017 to 2025). An uncommon variant of rhabdomyosarcoma characterized by the presence of whorls of spindle cells forming a storiform pattern. "Secondly, the infant/congenital subtype of spindle cell rhabdomyosarcoma harbours fusions of VGLL2::NCOA2 or VGLL2::CITED, which occur in up to two-thirds of cases, and rarer TEAD1::NCOA2 fusions have also been reported." (PMID 40983796, 2025). "Fusions between SRF and NCOA2 were detected in some spindle cell rhabdomyosarcomas, while fusions between SRF and NCOA1 or FOXO1 were recently found in “well differentiated” RMS." (PMID 38611033, 2024). "MEIS1::NCOA2 is a rare fusion gene that has been recently described in a subset of spindle cell rhabdomyosarcomas and multiple low-grade undifferentiated spindle cell sarcomas predominantly arising in the genitourinary and gynecologic tracts with no specific line of differentiation." (PMID 38678288, 2024). "Finally, in spindle cell rhabdomyosarcomas, fusions TEAD1::NCOA2 and VGLL2::NCOA2/CITED2 have been described." (PMID 38611033, 2024).
colorectal cancer (5 papers, 2015 to 2022). A primary or metastatic malignant neoplasm that affects the colon or rectum. "The LACTB2-NCOA2 fusion in colorectal cancer leads to disruption of NCOA2, which encodes an inhibitor of the Wnt/β-catenin pathway, thus acting to promote carcinogenesis." (PMID 26684754, 2015). "Additionally, the LACTB2-NCOA2 chimeric transcript detected in 6 of 99 (6.1 %) colorectal cancer cases led to disruption of NCOA2 expression, thus activating the Wnt/β-catenin pathway." (PMID 26684754, 2015). "NCOA2 is a negative growth regulator gene that represses the Wnt/beta-catenin pathway in colorectal cancer." (PMID 36248436, 2022).
prostate tumors (5 papers, 2012 to 2023). "An overexpression of NCOA2 in mouse prostate tumors led to the overactivation of PI3K/AKT and MAPK signals, thus promoting the tumor malignancy." (PMID 36836696, 2023).
Angiofibroma (3 papers, 2020 to 2025). A benign neoplasm of fibrous tissue in which there are numerous small and large, frequently dilated, vascular channels. "NCOA2 is involved recurrently in gene fusions associated with soft tissue tumors that include angiofibroma of soft tissue (AHRR::NCOA2) and spindle cell/sclerosing rhabdomyosarcoma (TEAD1::NCOA2 and VGLL2::NCOA2)." (PMID 37212282, 2023).
bladder cancer (3 papers, 2012 to 2026). "Clinically, reduced SIRT6 expression coupled with elevated NCOA2 and mitochondrial/β-oxidation markers correlates with metastatic progression in bladder cancer." (PMID 41943834, 2026).
endometrial cancer (3 papers, 2012 to 2019). Primary or metastatic malignant neoplasm involving the endometrium (mucous membrane that lines the endometrial cavity). "Sub-complex AML test for genetic association between the tag SNPs in the NCOA2 complex and endometrial cancer risk in the validation analysis." (PMID 22876322, 2012). "Although the genetic variation of the NCOA2 complex as a whole is marginally associated with endometrial cancer risk in the Swedish population, we failed to validate this finding in an independent study of subjects of European ancestry." (PMID 22876322, 2012). "Although the discovery analysis in our study demonstrated with marginal significance that the cumulative effects of multiple variants of NCOA2 complex may have a contribution to the risk of endometrial cancer, the association failed to be replicated in an independent sample." (PMID 22876322, 2012).
liver cancer (3 papers, 2017 to 2022). An epithelial or non-epithelial malignant neoplasm that arises from the liver. "This led to the identification of Steroid Receptor Coactivator 2 (SRC-2, also known as NCOA2, TIF2, GRIP1) as a novel gene that functions to restrain MYC-induced liver cancer." (PMID 28273073, 2017). "While we did not identify SB inactivation of Ncoa2 and Sav1 in our tumors, these genes were previously identified in liver cancer mouse models driven by SB mutagenesis in the presence of Myc activation or Pten loss." (PMID 33435458, 2021).
uterine tumour (3 papers, 2020 to 2025). "First, GREB1-rearranged uterine tumours as a group displayed a greater degree of genomic complexity with more extensive copy number alterations than conventional UTROSCTs, including those harbouring ESR1::NCOA2/3." (PMID 41424301, 2025).
COVID-19 (2 papers, 2020 to 2022). A disease caused by infection with severe acute respiratory syndrome coronavirus 2. "A previous study found that Jin Hua Qing Gan Granules regulate multiple signaling pathways via binding targets, such as PTGS2, HSP90AA1, and NCOA2, to prevent COVID-19." (PMID 35891565, 2022).
Ewing sarcoma (2 papers, 2023 to 2024). A small round cell tumor that lacks morphologic, immunohistochemical, and electron microscopic evidence of neuroectodermal differentiation. "HEY1::NCOA2 expression in eSZ cells did not affect the expression of Pthlh; its expression was enriched in the cell of origin of Ewing sarcoma in our previous model." (PMID 37212282, 2023).
gastric cancer (2 papers, 2022 to 2025). A primary or metastatic malignant neoplasm involving the stomach. "Conversely, the knockdown of NCOA2 has been shown to inhibit the proliferation, metastasis, and invasion of gastric cancer cells, primarily via the Wnt signaling pathway." (PMID 40575382, 2025).
Infertility (2 papers, 2024). "Some of the genes presented, such as CCSER1, GNAQ, NCOA2, SNRK, and TSPO, have been previously associated with fertility traits in livestock species or related to infertility in human patients (CEP78 and GPER1)." (PMID 38540441, 2024).
melanoma (2 papers, 2017 to 2022). A malignant, usually aggressive tumor composed of atypical, neoplastic melanocytes. "Specifically, we applied a mRNA panel consisting of KI67 (indicative of cell proliferation), POLR2A, BRCA1, MTOR, NCOA2, and NCOA3 to highly scattering and autofluorescent human melanoma skin biopsy FFPE tissues obtained from and characterized by the UCI Dermatopathology Center." (PMID 35013281, 2022).
metastatic disease (2 papers, 2021 to 2025). "Mutations in AR transcriptional cofactors and regulators may have influence, such as NCOA2 which is enhanced in 8% of primary and 37% of metastatic disease cases." (PMID 33599076, 2021).
pancreatic cancer (2 papers, 2019 to 2025). "The association between rs76748266 and NCOA2 gain replicated in pancreatic cancer (ORpancreatic = 6.47; Qpancreatic = 1.56 × 10−2)." (PMID 39945744, 2025).
pleural cancer (2 papers, 2019). A primary or metastatic malignant neoplasm affecting the pleura. "Interestingly, NCOA2 is widely known for its oncogenic role, and NCOA2 gene fusions, mutations, deletions, and insertions have been observed in multiple cancers including endometrial, cancer, and pleural cancer." (PMID 30941313, 2019).
Sepsis (2 papers, 2025). Sepsis is defined as life-threatening organ dysfunction caused by a dysregulated host response to infection. "The regulatory axis of HNF4A/NCOA2/GR/STAB1 could potentially serve as a therapeutic target for sepsis-associated lung damage." (PMID 39979267, 2025). "Therefore, we hypothesize that HNF4A may exert a regulatory role in the sepsis-associated lung injury by influencing NCOA2/GR-mediated gene transcription." (PMID 39979267, 2025). "Previous studies have also shown that conditional knockout of NCOA2 or GR leads to an increased mortality rate in mice suffering sepsis." (PMID 39979267, 2025). "HNF4A promotes M2 macrophage polarization via the NCOA2/GR/STAB1 axis and attenuates acute-phase gene expression, with its activation linked to improved outcomes in models of sepsis." (PMID 41169395, 2025). "Overall, this study revealed that the regulatory axis of HNF4A/NCOA2/GR/STAB1 affects macrophage polarization, thereby improving sepsis-induced lung damage." (PMID 39979267, 2025).
spindle cell sarcoma (2 papers, 2024 to 2025). A malignant mesenchymal neoplasm composed of spindle-shaped cells. "Taken together, the imaging, histologic, immunohistochemical, and molecular findings led to a diagnosis of a primary lung low-grade undifferentiated spindle cell sarcoma with MEIS1::NCOA2 fusion." (PMID 38678288, 2024). "Ultimately, given a completely negative metastatic workup, a diagnosis of lung primary low-grade undifferentiated spindle cell sarcoma with MEIS1::NCOA2 fusion was rendered." (PMID 38678288, 2024).
virus infection (2 papers, 2019 to 2025). "However, the biological roles of NCOA2 in virus infection remain elusive." (PMID 31751430, 2019).
Anxiety (1 paper, 2020). Intense feelings of nervousness, tension, or panic often arise in response to interpersonal stresses. "NCOA2-/- female mice, but not males, show decreased anxiety and motor coordination." (PMID 32449767, 2020).
cholestasis (1 paper, 2022). Impairment of the bile flow caused by obstruction within the liver, or outside the liver in the bile duct system. "Moreover, Q7R can also reduce TNF-α, IL-1β, PTGS1, PTGS2, NCOA2, and NF-κB levels and alleviate the inflammatory response caused by cholestasis." (PMID 36699093, 2022).
clear cell sarcoma (1 paper, 2024). A rare malignant neoplasm with melanocytic differentiation characterized by the presence of polygonal or spindle shaped clear cells. "These two forms of HEY1::NCOA2 fusion might be caused by splicing alterations, as an EWSR1::ATF1 fusion was identified in clear cell sarcoma, although we do not have any data." (PMID 39165647, 2024).
ependymoma (1 paper, 2021). A WHO grade II, slow growing tumor of children and young adults, usually located intraventricularly. "t‐distributed stochastic neighbor embedding analysis of DNA methylation data from two cases with C11orf95‐NCOA1 or ‐NCOA2 and a reference set of 380 CNS tumors revealed that these two cases were clustered together and were distinct from all subgroups of ependymomas." (PMID 33576087, 2021).
glomerulosclerosis (1 paper, 2020). A hardening of the kidney glomerulus caused by scarring of the blood vessels. "We speculated that NCOA2, as a nuclear regulatory factor, could induce the VEGF expression, which can induce renal interstitial fibrosis and glomerulosclerosis." (PMID 32884936, 2020).
meningioma (1 paper, 2023). A generally slow growing tumor attached to the dura mater. "At the same time, mRNA levels of AhR, ARNT, and NcoA2 in the meningiomas subjected to hypoxia as a result of the embolization were statistically significantly lower than those in the nonembolized meningiomas." (PMID 37305351, 2023). "Because the NcoA2 inhibits proteins of the bHLH/PAS family, such as HIF-1α, ARNT, and AhR, it is likely that in the molecular processes of meningioma ischemic hypoxia, AhR signaling probably plays a more important role than the HIF-1α pathway does." (PMID 37305351, 2023). "As revealed by our analysis of mRNA expression in samples of meningioma tissue subjected to hypoxic ischemic preconditioning, the expression of HIF-1α and its target genes (VEGF-A, c-Myc, and GLUT1) is not affected by this procedure, whereas AhR, ARNT, and NcoA2 expressions significantly decreases." (PMID 37305351, 2023).
muscle cancer (1 paper, 2024). A malignant neoplasm affecting the skeletal or smooth muscles. "Interestingly, NCOA2 fusion with PAX3 has been shown to inhibit myogenic differentiation in muscle cancer." (PMID 39009887, 2024).
neck tumor (1 paper, 2014). "RT-PCR and Sanger sequencing showed that exon 4 of HEY1 was fused to exon 13 of NCOA2 in the sample from the thigh lesion; we did not have spare material to perform a similar analysis of the neck tumor." (PMID 24839999, 2014).
pediatric cancer (1 paper, 2023). "When HEY1::NCOA2 was knocked down using human HEY1-specific shRNA sequences, genetic pathways associated with pediatric cancer and proteoglycan synthesis were affected." (PMID 37212282, 2023).
periodontitis (1 paper, 2025). An acute or chronic inflammatory process that affects the tissues that surround and support the teeth. "After integrating DNA methylation with transcriptome profiles, GRASP, HLA-DMB, HLA-DMA, CAB39, NCOA2 and TLE4 were identified as candidate genes in periodontitis PMNs." (PMID 40267082, 2025).
renal fibrosis (1 paper, 2022). A final common manifestation of a wide variety of chronic kidney diseases characterized by glomerulosclerosis and tubulointerstitial fibrosis. "The results suggested that 17 core compounds such as quercetin, kaempferol, luteolin, naringenin, and 23 core targets such as NCOA2, HSP90AA1, and PTGS1 might play an important role in JPYSF-treated renal fibrosis." (PMID 35656312, 2022).
retinal disease (1 paper, 2012). "Based on putative function and/or involvement in retinal disease, we selected 16 genes – Bach2, Cdr2, Dusp12, Esrrb, Gpsm2, Haus1, Kdm5b, Lman1, Lrp11, Lrrc2, Ncoa2, Plekha2, Ppargc1b, Trim36, Wisp1 and Zdhhc14." (PMID 22511886, 2012).
schizophrenia (1 paper, 2024). A major psychotic disorder characterized by abnormalities in the perception or expression of reality. "Additionally, we found a negative correlation between ERVWE1 and NCOA2 in GSE53987 and GSE25673, which may suggest a potential correlation between circ_0001810 and ERVWE1 in schizophrenia." (PMID 39543767, 2024).
tumor (48 papers, 2008 to 2025). "Significant African-ancestry-specific findings include an elevated tumour mutational burden, increased percentage of genome alteration, a greater number of predicted damaging mutations and a higher total of mutational signatures, and the driver genes NCOA2, STK19, DDX11L1, PCAT1 and SETBP1." (PMID 36045292, 2022). "The study also demonstrated that inhibiting p300 activity via a small molecule inhibitor led to reduction in TEAD1::NCOA2 colony formation along with suppressing tumor growth in the allograft model." (PMID 40599857, 2025). "The first was a congenital SSRMS tumor in the forearm of a 2-week-old girl with a TEAD1::NCOA2 gene fusion (case 7), and the second was an intraosseous SSRMS in the base of the skull of a 12-year-old boy with a FUS::TFCP2 gene fusion (case 8)." (PMID 40923514, 2025). "This evidence suggests that morphological features need to be taken into account when setting thresholds for the proportion of tumor cells with split signals in FISH analysis of NCOA2 rearrangement, especially on small biopsy specimens." (PMID 35832542, 2022). "Cytogenetically, AFST is characterized by the gene rearrangement of NCOA2, which results in the formation of a tumor-specific AHRR–NCOA2 fusion gene in most cases." (PMID 35832542, 2022). "Studies have deciphered that NCOA2 is an important tumor suppressor gene, and activation of NCOA2 is beneficial to inhibit the occurrence and development of HCC." (PMID 36578460, 2022). "The tumor cells were determined by FISH to have NCOA2 rearrangement and by RNA sequencing to harbor a GREB1-NCOA2 fusion." (PMID 32921307, 2020). "The proportion of macrophages was definite for AR (R = 0.379, P < .001), after adjusting for tumor purity, and similar results were illustrated for NCOA2 (R = 0.392, P < .001) and NCOA4 (R = 0.165, P < .001)." (PMID 31355524, 2019). "This revealed a tumor suppressor role for Steroid Receptor Coactivator 2/Nuclear Receptor Coactivator 2 (Src-2/Ncoa2) in liver cancer." (PMID 28273073, 2017). "These examples demonstrate that despite divergent clinical behaviour and outcomes between different diagnoses, the tumours commonly contain NCOA2 as a fusion partner." (PMID 25202377, 2014). "Retroviral insertions were present in the mouse homologs of 10 genes tagged in the zebrafish tumor samples: Brd2, Cirbp, Fgf8, Hexim1, Map2k5, Mmp14, Ncoa2, Slc30a5, Sox4, and Sox5." (PMID 21533036, 2011). "Another study identified PAX3::NCOA2 in a patient tumor diagnosed with embryonal RMS." (PMID 40599857, 2025). "This is because NCOA2-positive cells may be rare and are only detected in a limited number of tumor cells." (PMID 39432588, 2024). "Likewise, KMT2C, CREBBP, and NCOA2 were identified to demonstrate tumor-suppressive roles in the initiation and progression of human cSCC." (PMID 36980718, 2023). "Although the incidence of NCOA2 rearrangement by FISH study in AFST is high, the proportion of tumor cells with NCOA2 split signals may be low." (PMID 35832542, 2022). "Indeed, although not represented on either of the curated CGC or TSGdb lists, several genes (e.g., Cep350, Ncoa2, and Usp9x) have all been observed in other SB tumor screens and experimentally validated to be TSGs within mouse models and/or human cancer cells." (PMID 33435458, 2021). "Next, we investigated whether down-regulation of CREBBP, KMT2C or NCOA2 could promote tumor progression in cuSCCs." (PMID 34398873, 2021). "In a follow-up study characterizing spindle-cell infantile/pediatric RMS tumor specimens, additional fusions were identified including VGLL2::NCOA2, VGLL2::CITED2, TEAD1::NCOA2, and SRF::NCOA2." (PMID 40599857, 2025). "AHRR is a recognized tumor suppressor that regulates the activity of AHR, whereas NCOA2 acts as a transcriptional co-activator of nuclear hormone receptors." (PMID 39432588, 2024).
tumor (continued). "Other AR-related genes (FOXA1, NCOA2, SPOP) exhibited minimal differences in transcript expression in either metastatic site relative to the primary tumor." (PMID 39349591, 2024). "These gene fusions, such as GREB1::NCOA2 and ESR1::NCOA2, result in the aberrant activation of estrogen signaling pathways, driving the proliferation and survival of tumor cells." (PMID 38276058, 2024). "Comparison of gene expression profiles between tumor cells and chondrogenic progenitors introduced with HEY1::NCOA2 identified 23 common upregulated genes." (PMID 37212282, 2023). "AHRR is a putative tumor suppressor and regulates the activity of AHR, while NCOA2 functions as a transcriptional coactivator for nuclear hormone receptors." (PMID 35832542, 2022). "Functional analysis confirms an oncogenic role for the ZMIZ genes, and tumor suppressive roles for KMT2C, CREBBP and NCOA2, in the initiation or progression of human cuSCC." (PMID 34398873, 2021). "In contrast, NCOA2, VEGFA, ACPP, KLF4, and TMPRSS2 had significantly higher tumor vs. normal ratio in BCR cases." (PMID 31741711, 2019). "Patients aged <1 year with VGLL2, SBF, TEAD1, and NCOA2 gene fusions had a better prognosis, whereas patients with a MYOD1 gene mutation demonstrated stronger tumor aggression and higher mortality, regardless of age." (PMID 36686750, 2022). "Of note, it seems to be a fusion driven tumor, with Hes Related Family BHLH Transcription Factor With YRPW Motif 1: nuclear receptor coactivator 2 (HEY1-NCOA2) and interferon regulatory factor 2 binding protein 2: caudal type homeobox 1 (IRF2BP2-CDX1) fusions having recently been described." (PMID 36158667, 2022). "All three cuSCC cell lines demonstrated enhanced in vivo tumor growth with KMT2C or NCOA2 depletion compared to cells with a non-targeting control shRNA (1-factor ANOVA, q<0.05)." (PMID 34398873, 2021). "However, alternative HEY1::NCOA2 fusions have not been reported in this tumor." (PMID 39165647, 2024).